NCAM1 (neural cell adhesion molecule 1)
Diseases named in the same sentence as NCAM1 in open-access papers (continued):
Sharing a sentence is not in itself a finding about the gene and the disease.
schizophrenia (52 papers, 2011 to 2026). A major psychotic disorder characterized by abnormalities in the perception or expression of reality. "Numerous studies have assumed NCAM1 as a susceptibility factor for several neuropsychiatric disorders, including depression, bipolar disorder, and schizophrenia." (PMID 39897774, 2025). "NCAM1 has been implicated in various human psychiatric disorders, including bipolar affective disorder, schizophrenia, and autism spectrum disorders." (PMID 40653016, 2025). "NCAM1 (Neural Cell Adhesion Molecule 1) belongs to the immunoglobin superfamily, and has been considered a susceptibility gene for schizophrenia and bipolar disorder." (PMID 32922442, 2020). "Additionally, several genetic variants in the NCAM1 gene have been linked to an increased risk of the development of bipolar disorder, schizophrenia, autism, as well as other conditions, such as suicidal behavior and cannabis use and depression." (PMID 39897774, 2025). "NCAM1 has also shown genetic association with bipolar disorder, schizophrenia and neurocognition." (PMID 24651862, 2014). "Autoimmune encephalitis (AE) has been linked to various autoantibodies, with anti-neural cell adhesion molecule 1 (NCAM1) antibodies recently identified in patients with schizophrenia." (PMID 41694384, 2026). "Commercially available anti-NCAM1 antibodies and serum samples from patients with schizophrenia previously confirmed to be anti-NCAM1 seropositive were used as positive controls." (PMID 40687082, 2025). "The significance of NCAM is even more evident in its relevance in schizophrenia mouse models, such as NCAM1 null mice and in the maternal deprivation mouse model also NCAM expression is seen to be reduced." (PMID 34494935, 2021). "When active, the predicted enhancer element in the schizophrenia-associated locus affects transcription of both DRD2 and NCAM1, with a more prominent effect on the transcription of the NCAM1 gene." (PMID 31616042, 2020). "We observed decreased sensitivity of DT phase-associated GPC1 and NCAM1, suggesting decreased expression of membrane-bound GPI-anchored GPC1 and NCAM1 in schizophrenia." (PMID 30664618, 2019). "We examined expression of known GPI-APs previously associated with schizophrenia, GPC1, NCAM1, MDGA2, and EPHA1." (PMID 30664618, 2019). "Other groups have shown association with schizophrenia in Japanese and Chinese cohorts in the promoter region of ST8SIA2, which was selected as a candidate gene after NCAM1 was implicated in disease risk." (PMID 24651862, 2014). "CSF APP and GDNF levels were decreased in patients with schizophrenia, while CSF APP and NCAM-1 levels were decreased in patients with BD, compared with healthy controls." (PMID 32439851, 2020). "CSF amyloid precursor protein (APP) and glial cell-derived neurotrophic factor (GDNF) levels were significantly lower in patients with schizophrenia, and CSF APP and neural cell adhesion molecule (NCAM)-1 levels were significantly lower in patients with BD, than in healthy controls (all p < 0.05)." (PMID 32439851, 2020). "In support of this hypothesis, anti-NCAM1 autoantibodies disrupting the interaction of GDNF with NCAM1 could be detected in 5.4% of schizophrenia patients and injection of these antibodies precipitated schizophrenia-related symptoms in mice." (PMID 38674063, 2024). "NCAM1 has previously been implicated in a number of neuropsychiatric disorders, including schizophrenia, and our analysis identifies NCAM1 as another plausible target, despite not being categorized as a GRB target (it’s predictive value is just below the threshold)." (PMID 31616042, 2020).
leukemia (47 papers, 2008 to 2026). A malignant (clonal) hematologic disorder, involving hematopoietic stem cells and characterized by the presence of primitive or atypical myeloid or lymphoid cells in the bone marrow and the blood. "Additionally, NCAM1 encodes a protein that is a member of the immunoglobulin family and has been predominately studied as it portends therapy resistance and cell proliferation in leukemia and lung cancer." (PMID 36675007, 2023). "NCAM1 (CD56) is found with a link to tumor progression, can promote leukemogenesis and confer drug resistance in leukemia." (PMID 39420637, 2024). "AP000880.1 is possibly related to TTC12 and NCAM1 gene, which in turn plays an important role in the initiation of leukemia." (PMID 35719911, 2022). "Additionally, in the comparison between CSF + LM (leukemia) and CSF − LM, several significant differences in protein profiles (such as NCAM1, sCD3, sCD19, sCD8A, MKI67A, among others) were related with the pathology." (PMID 35053611, 2022).
lung carcinoma (47 papers, 2004 to 2025). "The association of the sixth biomarker (expression level of NCAM1 gene) with the response to ICI immunotherapy in lung cancer was also previously reported." (PMID 39723204, 2024). "The lung cancer exhibited strong staining for NCAM1, NSE, Syn, and CgA, and the observed reductions in menin were associated with high Ki67 proliferation indexes in tumors." (PMID 32081882, 2020). "The prognostic value related to the worse prognosis of IL-8, SCG2, NCAM1, CNTN1, CADM1, NPTX1, and APOD tumor transcripts were evaluated in seven lung cancer transcriptome datasets (validation set)." (PMID 31455042, 2019). "The regulatory potential of NE-DMRs was further validated in vitro using paired ATAC- and RNA-seq and revealed both proximal and distal regulatory elements of canonical NE-marker genes such as CHGA, NCAM1, INSM1, as well as a number of novel candidate markers of NE lung cancer." (PMID 32707835, 2020).
small cell lung carcinoma (47 papers, 1992 to 2025). Small cell lung cancer (SCLC) is a highly aggressive malignant neoplasm, accounting for 10-15% of lung cancer cases, characterized byrapid growth, and early metastasis. "Elevated expression level of CD56 (neural cell adhesion molecule; NCAM1) has been detected in a range of cancers and it is associated with the diagnosis or prognosis of small cell lung cancer, as well as Merkel cell-carcinoma and ovarian cancer." (PMID 37495566, 2023). "Several authors have reported that NCAM1 is expressed in the vast majority of small cell lung carcinomas." (PMID 39408967, 2024). "Antibodies have proven to be effective vehicles for the targeting of NCAM1, and various antibody–drug conjugates have been developed to deliver cytotoxic substances specifically to small cell lung carcinoma cells via NCAM1 targeting." (PMID 39408967, 2024). "Several mechanistic investigations have shown that NEUROD1 effectors boost the survival, migration, and proliferation of small-cell lung cancer (SCLC) cells by activating cell surface receptor tyrosine kinase tropomyosin-related kinase B (TRKB) and neural cell adhesion factor (NCAM1)." (PMID 39858036, 2025).
small cell carcinoma (41 papers, 2007 to 2026). A neuroendocrine carcinoma composed of small malignant cells which are often said to resemble "oat cells" under the microscope. "These phenotypically similar, small cell neuroendocrine cancers (SCNCs) are classified as high-grade, poorly differentiated small cell carcinomas that commonly express neuroendocrine markers like chromogranin A (CHGA), neural cell adhesion molecule 1 (NCAM1), and synaptophysin (SYP)." (PMID 39589879, 2024).
acute myeloid leukemia (37 papers, 2010 to 2026). Acute myeloid leukemia (AML) is a group of neoplasms arising from precursor cells committed to the myeloid cell-line differentiation. "Furthermore, NCAM1 is associated with immune evasion in acute myeloid leukemia (AML), where it promotes leukemogenesis and drug." (PMID 40971385, 2025). "NCAM1 helped cancer cell’s perineural invasion and promoted leukemogenesis and drug resistance in acute myeloid leukemia." (PMID 35550610, 2022). "Neural cell adhesion molecule one (NCAM1) has not been extensively investigated in BCa, but there are studies that link its expression with drug resistance in acute myeloid leukemia, pleuropulmonary blastoma, and cervical intraepithelial neoplasia." (PMID 35884419, 2022).
viral infections (36 papers, 2009 to 2024). "Downregulation of NCAM1 is associated with decreased cell adhesion capacity, enhanced tumor cell invasiveness and is triggered in other viral infections." (PMID 30642035, 2019). "NCAM1 is expressed in NK cells and serves as a host protective component in the local innate immune response against viral infections." (PMID 28427244, 2017). "Increased numbers of circulating NCAM1 negative NK cells have also been found in patients with various virus infections and among elderly, but not in healthy individuals." (PMID 35008799, 2021).
depression (31 papers, 2012 to 2026). "This genomic region that harbors multiple known depression-associated genes (e.g., NCAM1, TTC12, DRD2) remained significant for depression and ischemic stroke." (PMID 40949012, 2025). "NCAM1 variants have been previously associated with alcohol, cannabis and smoking behaviors, mathematical ability, and anxiety and depression, among other traits." (PMID 37173343, 2023). "By integrating data from the literature, we revealed 4 genes of interest (GNB3, CNR1, MTHFR, and NCAM1) that were likely to be associated with the aetiology of both MI and depression." (PMID 31185929, 2019). "In conclusion, using literature mining methods, the GNB3, CNR1, MTHFR, and NCAM1 genes were identified and directly or indirectly implicated in the regulation of MI and depression." (PMID 31185929, 2019). "Numerous studies have suggested that NCAM1 is a gene of interest associated with the pathogenesis of depressive disorder." (PMID 31185929, 2019). "Additionally, NCAM1-related probes were associated with depression in both GSE98793 and GSE46743 cohorts but the direction of the association is not concordant." (PMID 39897774, 2025). "Moreover, experimental studies have shown deficits in NCAM1 to be associated with depression-like phenotype and reduced antidepressant efficacy in animal models." (PMID 39897774, 2025). "Interestingly, genome-wide association study of UK biobank revealed positive link between neural cell adhesion molecule (NCAM)-1 gene as a high risk loci for depression and IBS or Hp-relevant PUD/gastroesophageal reflux disease." (PMID 37291550, 2023). "The authors noted the down-regulation of NCAM1, which supported the hypothesis that major depression is associated with impaired cellular proliferation and plasticity." (PMID 35565902, 2022). "The present study identified six protein-coding genes associated with depression and primarily involved in inflammation (TNXB), neuroplasticity (NCAM1 and LTBP3), immune response (BTN3A2), cell survival (DAG1) and circadian clock modification (FHIT)." (PMID 39897774, 2025). "Eight SNPs corresponding to six protein-coding genes (TNXB, NCAM1, LTBP3, BTN3A2, DAG1, FHIT) were identified that were highly associated with depression." (PMID 39897774, 2025). "Our findings confirmed previous evidence for TNXB- and NCAM1 in the pathophysiology of depression and suggested four new potential candidate genes (LTBP3, BTN3A2, DAG1 and FHIT) that warrant further investigation." (PMID 39897774, 2025). "Our findings confirmed previous evidence for TNXB- and NCAM1 in the pathophysiology of depression and suggested new potential candidate genes (LTBP3, BTN3A2, DAG1 and FHIT) that warrant further investigation." (PMID 39897774, 2025). "We have identified six protein-coding genes associated with depression and primarily involved in inflammation (TNXB), neuroplasticity (NCAM1 and LTBP3), immune response (BTN3A2), cell survival (DAG1) and circadian clock modification (FHIT)." (PMID 39897774, 2025). "A study was also published, in which the search for factors common to depressive disorders and lichen planus highlighted two genes (NCAM1 and CD4) identified as common to the pathomechanism of both disorders." (PMID 38892934, 2024). "Ncam1 has been investigated in the context of depression, regarding its multicellular organismal response to stress, learning and memory, and modulation of synaptic transmission." (PMID 35565902, 2022). "In the present study, the NCAM1 gene was mainly expressed in the cerebral cortex and amygdala in the brain, which are involved in the pathogenesis of depression." (PMID 31185929, 2019). "Dysregulated NCAM1 has been found in patients with major depression." (PMID 37076499, 2023). "Taken together, these results suggest that the overexpression of the GNB3, CNR1, MTHFR, and NCAM1 genes may contribute to the development of MI and depression and may play a role in the interaction between these two diseases." (PMID 31185929, 2019).
depression (continued). "GNB3, CNR1, MTHFR, and NCAM1 are putative new candidate genes that may influence the interactions between MI and depression, and may represent potential targets for therapeutic intervention." (PMID 31185929, 2019). "Hence, this evidence may have implications for the role of NCAM1 in communication between MI and depression that warrants further exploration." (PMID 31185929, 2019). "We identified pleiotropic loci 11q23.2 (mapped gene: NCAM1/DRD2) and 18q12.2 (mapped gene: CELF4) in neuroticism and IBS/GERD, supporting the genetic overlap between neuroticism and depression." (PMID 40226707, 2024). "In addition, using the BITOLA system, genes neural cell adhesion molecule 1 (NCAM1) and CD4 were identified as potential candidate genes in the interaction between depression and oral lichen planus." (PMID 31185929, 2019). "The present study additionally contributed to the understanding of this complex system, demonstrating that KLK8 mediated the ectodomain shedding of NCAM1, which may represent a potent mechanism for neuronal apoptosis in the hippocampus during the pathogenesis of CUMS-induced depression." (PMID 37076499, 2023).
prostate carcinoma (31 papers, 2001 to 2025). A carcinoma that arises from epithelial cells of the prostate gland. "Interestingly, earlier studies have shown that overexpression of Hox genes or NCAM1 is linked with either a NE-like transformation or the development of AR signaling inhibitor-resistant prostate cancer." (PMID 39183332, 2024). "NCAM1 (CD56) was significantly (p-value < 0.05) downregulated in prostate cancer lung metastases." (PMID 39146303, 2024). "Although the main function of Schwann cells is to maintain axonal integrity, Schwann cells have been shown to stimulate pancreatic and prostate cancer cell invasion in an integrin-dependent manner and to promote perineural invasion via neural cell adhesion molecule 1 (NCAM1) signaling." (PMID 33672617, 2021). "Furthermore, enriched pathway terms were mainly associated with ECM–receptor interactions, RAF-independent MAPK1/3 activation, collagen biosynthesis and modifying enzymes, prostate cancer, platelet homeostasis, NCAM1 interactions, and signaling by NTRKs." (PMID 32906679, 2020). "We then reviewed 8,194 prostate cancer cases with available immunohistochemistry reports and found 2.3% cases (n = 189) that showed at least one of the NE markers (chromogranin A, synaptophysin, and neural cell adhesion molecule 1) being positive in at least 5% of epithelial cells." (PMID 36033483, 2022). "We retrospectively reviewed all 8,194 prostate cancer cases with available immunohistochemistry reports and found 2.3% (n = 189) with any one of the NE markers (CHGA, SYP, and NCAM1) being positive in at least 5% of epithelial cells." (PMID 36033483, 2022). "Our study presents data from multiple prostate cancer patients, demonstrating the CoDuCo assay’s ability to visualize diverse resistance mechanisms, such as neuroendocrine differentiation markers (SYP, CHGA, NCAM1) and AR-V7 expression." (PMID 39550585, 2024). "Therefore, we examined the impact of ELAVL3 overexpression in prostate cancer cell lines and discovered that it effectively stimulated the expression of neuroendocrine markers, alongside MYCN, NCAM1, and SYP when compared with vector control." (PMID 38016952, 2023). "Prostate cancer with neuroendocrine differentiation is typically defined by the heterogeneous histological expression of several NE markers in at least 5% of epithelial cells, including chromogranin A (CHGA), synaptophysin (SYP), neural cell adhesion molecule 1 (NCAM1), and enolase 2 (ENO2)." (PMID 36033483, 2022).
ovarian carcinoma (25 papers, 2011 to 2026). A malignant neoplasm originating from the surface ovarian epithelium. "Previous studies have reported that PQBP1 regulates AS of BCL‐X in human A549 cells and Ncam‐1 in mouse neurons, and our present work provides strong evidence that PQBP1 regulates AS of apoptotic genes, including BAX, in ovarian cancer cells." (PMID 38342602, 2024).
pancreatic cancer (24 papers, 2010 to 2025). "A study using oncogenic K-ras pancreatic cancer cell lines identified increased levels of polysialylated NCAM1 expression, which interacts with E-cadherin to create steric hindrance of homophilic binding and decrease cell adhesion." (PMID 31921388, 2019). "Among these we found that up regulation of S100A4, NCAM1 and LIMK1 had already been associated with metastatic behavior in pancreatic cancer." (PMID 22078386, 2011). "NCAM1, also known as CD56, has been used as an IHC diagnostic and prognostic biomarker with high sensitivity and specificity to differentiate PanNETs from other pancreatic cancers." (PMID 40217502, 2025). "To investigate the potential of TLR2 and TLR9 inhibition in pancreatic cancer cells and its efficacy in tumor cell death, we developed pCMV Myc NCAM1, pCMV Myc TLR2, and pCMV Myc TLR9 plasmids expressing NCAM1 intrabodies (control intrabodies) and TLR2- and TLR9-specific intrabodies." (PMID 38390872, 2024).
glioblastoma (21 papers, 2006 to 2025). The most malignant astrocytic tumor (WHO grade IV). "Recent proteomic studies allowed identification of the Neural Cell Adhesion Molecule (NCAM1) as a potential ZIKV receptor in Vero cells and human glioblastoma cells U-251 MG." (PMID 35214042, 2022). "We identified Neural Cell Adhesion Molecule (NCAM1) as a potential ZIKV receptor and further validated it through overexpression, knockout, and inhibition of NCAM1 in Vero cells and human glioblastoma cells U-251 MG." (PMID 32753727, 2020).
Wilms tumor (21 papers, 2008 to 2025). An embryonal neoplasm characterized by the presence of epithelial, mesenchymal, and blastema components. "Both fractions of Wilms' tumor (NCAM1+ADLH1+ and NCAM1+ADLH1−) showed a strong overexpression of the mesenchymal isoform, and all fractions of the fetal cells grown in SFM (NCAM+CD133−, NCAM+CD133+, and NCAM−CD133+) expressed the epithelial isoform." (PMID 28552604, 2017). "This was recently evident in Wilms' tumour for which an additional marker (ALDH) within the NCAM1+ fraction was used to more precisely pinpoint cancer stem/initiating cells in the tumour." (PMID 23996934, 2013). "Furthermore, recent studies in pediatric kidney cancer, Wilms’ tumor (nephroblastoma), point to an embryonic renal stem/progenitor initiating cell that fails to differentiate properly and undergoes malignant transformation to a NCAM1+/ALDH+CSC." (PMID 26210994, 2015).